AGO2 (argonaute RISC catalytic component 2)
Diseases named in the same sentence as AGO2 in open-access papers (continued):
Sharing a sentence is not in itself a finding about the gene and the disease.
infection (126 papers, 2008 to 2025). The state of being infected such as from the introduction of a foreign agent such as serum, vaccine, antigenic substance or organism. "Similar to the situation in Aag2 Ago2-deficient cells, the viability of C6/36 was reduced by 60 % and 80 % after infections with BinJV and BinJ-ZIKV, respectively (p < 0.0001)." (PMID 39845567, 2025). "As a countermeasure, RV was found to trigger proteasomal degradation of AGO2, the catalytic effector of the siRNA‐mediated RNAi in mammalian cells, during the early hours of infection, leading to the loss-of functionality of siRNA-based RNAi." (PMID 36189370, 2022). "Immune defence is mediated by RNA interference (RNAi); AGO2 was recently implicated in mammalian anti‐infection defence as a result of its role in miRNA biogenesis and function." (PMID 34632719, 2021). "Surprisingly, they did not observe any qualitative phenotypic difference of Dcl, Ago1 and Ago2 mutants during infection of the susceptible wheat cultivar Bobwhite." (PMID 34208898, 2021). "In contrast, AGO2 silenced N. benthamiana plants with TBSV (a close relative of the CymRSV) infection caused severe symptoms." (PMID 33925878, 2021). "During pathogenic infection, siRNA-like traces like the 2-fold up-regulation of the core RNAi genes Ago-2 and Dcr-2 as well as a peak of 20 nt small RNAs were observed." (PMID 25816294, 2015). "Moreover, the viability of these infected Aag2 Ago2-deficient cells was significantly lower compared to WT Aag2 cells, displaying 60 % and 80 % reductions in viability after infections with BinJV and BinJ-ZIKV, respectively (p < 0.01)." (PMID 39845567, 2025). "Although we did not see changes in miR-200b and miR-429 levels upon reactivation, these miRNAs were highly abundant and Ago2-associated in lytic infection in AGS cells, suggesting that they might play roles in lytic infection." (PMID 40674434, 2025). "However, defective fly Ago-2, in Drosophila melanogaster, is susceptible to infection with Drosophila C virus and cricket paralysis virus." (PMID 34715923, 2021). "In summary, our integrated approach combining RNA sequencing and fPAR-CLIP demonstrates that nuclear AGO2 is crucial for the virus to subvert host immune responses and to ensure a successful infection." (PMID 40219968, 2025). "In the early stages of infection, PoRV triggers the degradation of AGO2 through its NSP1, thereby inhibiting the siRNA-mediated RNAi response." (PMID 40792103, 2025). "We observed robust nuclear translocation of AGO2 upon infection with PR8-IAV, particularly at MOI 2 or higher, while the total levels of AGO2 did not change." (PMID 40219968, 2025). "ago2 mutants exhibit heightened susceptibility to Cucumber mosaic virus (CMV) and Turnip crinkle virus (TCV), and AGO2 expression is induced upon infection, indicating its role in sRNA-mediated systemic RNAi defense against viral spread." (PMID 41550334, 2025). "Another study revealed the positive role of Ago2 in encephalitic alphavirus replication and infection, suggesting the role of RNAi machinery in alphavirus replication." (PMID 36851776, 2023). "The three cell types were infected with the SARS-CoV-2 delta variant at an MOI of 0.1, and mRNA expression levels of AGO2, DICER1, DGCR8, DROSHA, and XPO5 were measured 24 h and 48 h after infection." (PMID 37243263, 2023). "The expression level of Ago1 was selectively and strongly upregulated, while the Ago2 level remained unaltered in infected cells, both at 24 and 48 h post-infection." (PMID 38098491, 2023). "We report that Ago2 disruption severely impairs the degradation of viral dsRNA, resulting in high infection intensities in Ago2−/− mutants, which demonstrates the essential role of Ago2 in the mosquito siRNA pathway." (PMID 37723154, 2023). "mRNA level changes of DICER1, DGCR8, and XPO were approximately 2-fold, and of AGO2 approximately 4.6-fold, 24 h after infection." (PMID 37243263, 2023).
infection (continued). "On the other hand, infection of Vero E6 cells with SARS-CoV-2 impacted mRNA levels of AGO2, DICER1, DGCR8, and XPO5 at 24 h." (PMID 37243263, 2023). "For ago2, the gene was significantly upregulated on days 1, 2, and 3 after infection (p = 0.0030, <0.0001, and <0.0001, respectively), while for dcr2 an upregulation was observed on days 2 and 3 (p = 0.017 and <0.0001, respectively)." (PMID 37243270, 2023). "Here we show that siRNA pathway disruption by CRISPR/Cas9-based Ago2 knockout impaired the mosquitoes’ ability to degrade arbovirus RNA leading to hyper-infection accompanied by cell lysis and tissue damage." (PMID 37723154, 2023). "Infection of these plants with PepMV resulted in more severe symptoms than those exhibited by ago2 mutants." (PMID 37603044, 2023). "Genes involved in RNAi-mediated antiviral defense, such as DCL2, DCL4, RDR1 and AGO2 were upregulated at the onset of infection (7 dpi) and showed the highest levels of induction at 21 dpi." (PMID 38110861, 2023). "Infection of ago2/rdr6 plants with PepMV produced symptoms that were more severe than those shown by any of the single mutants." (PMID 37603044, 2023). "DENV replication is modulated by RNAi at different infection stages because the knockdown of key RNAi factors dcr-2 and ago-2 in Ae." (PMID 36296190, 2022). "For instance, L. pneumophila releases EVs containing sRNAs both in vitro and in vitro during infection; these sRNAs modulate the host innate immune response in argonaute-2 (Ago2)-dependent manner." (PMID 36619166, 2022). "The most notable example is AGO2 which undergoes degradation during the early hours of infection but is rescued later on and relocates to the viroplasmic niche." (PMID 36189370, 2022). "For the arthropod-borne alphavirus Semliki Forest virus (SFV), the magnitudes of the increase in infection were similar in Dcr2 and Ago2 knockout cells." (PMID 35171691, 2022). "To evaluate the impact of Ago2 knockdown on the health of young adult skeletal muscles, we collected TA muscles at 3 months post-infection for histological analysis." (PMID 35301367, 2022). "Dicer-2 (Dcr2) and Argonaute 2 (Ago2) genes are critical factors in response to AcMNPV infection in Sf9 cells, and their transcription level will increase after infection." (PMID 36204465, 2022). "We show that the parasite fhe-miR-125b loads onto the mammalian Argonaut protein (Ago-2) within macrophages during infection and, therefore, propose that it mimics host miR-125b to negatively regulate the production of inflammatory cytokines." (PMID 33762636, 2021). "Infection of Ago2 knockout cell line with alpha- and bunyaviruses resulted in an increase of viral replication, but not in the case of ZIKV." (PMID 34205194, 2021). "Here we provide proof that exogenous, worm-derived miRNA is delivered into macrophages, probably via exosomes, during infection and loads onto host Ago2." (PMID 33762636, 2021). "The more severe symptoms upon SPMMV infection on homozygous AGO2−/− mutant compared with the wt N. benthamiana plants and the inducible nature of AGO2 highly suggested the involvement of AGO2 in the antiviral defense against the SPMMV." (PMID 33925878, 2021). "First, to investigate a potential implication of the RNAi pathway, we performed a knock-down of the AGO2 protein prior to the infection of NoDice cells expressing either WT, N1 or N3 FHA:DICER." (PMID 33984068, 2021). "Resubstituting Ago2 in the AF525 cell line through transfection of a myc-Ago2 expression construct prior to SFV6-2SG-Nluc infection (MOI 0.5), resulted in a decrease in luciferase compared to control cells (transfection of myc-eGFP construct)." (PMID 34205194, 2021). "We further show that infection with NoVΔB2 or NoVmB2 induced in vivo production of vsiRNA-RISC active to direct Ago2-mediated, vsiRNA-guided specific RNA cleavage in an in vitro slicing assay." (PMID 32753500, 2020).
infection (continued). "Importance of Ago2 dephosphorylation in the infection process was studied further in Ago2‐depleted cells by expressing either the wild‐type Ago2 or phosphorylation defective Y529F Ago2 mutant co‐transfected either with siCon or siPP2A." (PMID 32031337, 2020). "Based on the present findings, DCL2, DCL4 and AGO2 are involved in tolerance to infection with PVX and PVY in tomato." (PMID 33032637, 2020). "Following IAV-WSN infection, we detected a strong fluorescence signal of AGO2 in the nucleus of infected 293T cells ectopically expressing Flag-AGO2." (PMID 33281788, 2020). "We observed that Wolbachia protects AGO2 silenced mosquitoes in similar extent as control mosquitoes (dsFLUC), since both groups presented low infection rates." (PMID 32784948, 2020). "RISCs that include AGO1, 2, 3, 4, 5, and 9 can bind to virus sRNA and Arabidopsis AGO5 can bind potato virus X (PVX) sRNA in N. tabacum and suppress the infection thereof, but only in the presence of an intact AGO2 interaction." (PMID 32528501, 2020). "We evaluated the mRNA expression levels of Dcr-2, Ago-2, and rp49 (housekeeping gene) by qPCR at four time points post-infection." (PMID 32194567, 2020). "We next performed an immunofluorescence staining assay to investigate the subcellular localization of AGO2 in 293T cells after IAV-WSN infection." (PMID 33281788, 2020). "It is possible that this results in a shift in the AGO1/AGO2 balance leading to the unmasking of AGO2-dependent defense during PVA infection." (PMID 33031436, 2020). "The high amounts of secondary siRNAs produced from NBR1 during infection correlated with high transcript levels as previously shown with AGO2." (PMID 33230160, 2020). "On the contrary, during infection, Leishmania is known to upregulate the binding of Ago2 with miRNAs." (PMID 32031337, 2020). "We have demonstrated that Arabidopsis AGO2 is strongly induced upon infection by Pseudomonas syringae pv tomato (Pst) carrying an effector protein, avrRpt2, and positively regulates plant antibacterial immunity." (PMID 30783097, 2019). "While AGO2 positively regulates plant immunity, it was unclear how the AGO2 protein is regulated when it is mostly needed during infection." (PMID 30783097, 2019). "Although the AGO2 protein accumulated to a higher level after bacterial challenge, less sDMA of AGO2 was detected after infection and this decrease was correlated with the decreased level of PRMT5." (PMID 30783097, 2019). "Evidence from one previous study indicates that human miRNAs complexed with human AGO2 are translocated into the parasite cytoplasm to function as negative regulators of the infection." (PMID 30646930, 2019). "It was found that DCR2 and AGO2 transcript levels were significantly increased in the midgut with DENV infected blood meal in the early days of infection, but the levels were equalized in later stages." (PMID 31200426, 2019). "Increased expression of dcr-2 and ago-2 mRNA was observed during early infection of Ae. aegypti mosquitoes with DENV-2 while during later stages also TSN mRNA was induced." (PMID 31354527, 2019). "For both SINV and SFV infections, vpiRNAs with ping-pong characteristics were also found in immunoprecipitates of Ago-2." (PMID 31354527, 2019). "Possible proviral functions of ago-2 and ago-3 were also revealed during infections with ZIKV in Aag-2 cells." (PMID 31354527, 2019). "Of interest is the observation that infections by Wolbachia can protect RNAi mutants (dcr-2, ago-2, r2d2) against infection by DCV and FHV." (PMID 29723993, 2018). "Plants that later recovered from infection showed increased accumulation of AGO2 protein at early stages of infection." (PMID 30450108, 2018). "We complemented these bioassays by testing the impact of downregulation of a key component in the siRNA pathway (AGO2), on GpSGHV infection in G. pallidipes." (PMID 30470195, 2018).
infection (continued). "IIV-6 infection of dcr-2, r2d2 or ago-2 mutant flies resulted in higher mortality, which, however, was accompanied with only a modest increase in viral titers." (PMID 29723993, 2018). "In this study, we identified four wound inflammation‐related Ago2‐miRNAs (miR‐139‐5p, miR‐142‐3p, miR‐142‐5p, and miR‐223) and show that miR‐223 is critical for infection control." (PMID 30171089, 2018). "In accordance with these results, differential regulation of RNAi-genes, including dcr2 and ago2, has been reported in different tissues of the bumblebee upon infection with the Israeli Acute Paralysis Virus42." (PMID 29403066, 2018). "In another report, D. melanogaster defective for the AGO2 were found to be hypersensitive to infections by DCV, an infection which also supported a 1000-fold increased production of progeny virus." (PMID 30470195, 2018). "After four weeks, the wild-type plants almost completely recovered from the infection, while the ago2 mutants died by that time." (PMID 28432338, 2017). "In conclusion, our results demonstrate for the first time that normal RBCs display an innate ability to resist infection by P. falciparum parasite by releasing Ago2-miRNA complexes via MPs into iRBCs." (PMID 28831191, 2017). "Ago2 was immunoprecipitated at 48 hpi following infection with ZIKV (MOI 1) and the captured small RNAs were sequenced." (PMID 29040304, 2017). "RDR6 and HEN1 were induced earlier (6 and 12 hai, respectively) than AGO2 (8 dai), whereas the Dicer-like nucleases genes were suppressed during the infection." (PMID 27933078, 2016). "A real-time quantitative RT-PCR (RT-qPCR) assay showed that the transcript levels of the siRNA core components DCR2 and AGO2 increased about 3-fold after RGDV infection in VCMs at 72 h postinoculation (hpi)." (PMID 26864546, 2016). "Levels of the viral 3C protein at 24 h post-infection were decreased 25–35% upon knockdown of Ago2 or HuR; the reduction in 3C was 2.5-fold upon double knockdown of Ago2 and HuR." (PMID 26451954, 2015). "We show that high molecular weight complexes containing Ago2 are present in cells of the mosquito's open circulatory system prior to infection." (PMID 21356105, 2011). "We have demonstrated that Ago2 expression is essential in mosquitoes for modulation of alphavirus (Togaviridae) infection of An. gambiae and Ae. aegypti." (PMID 19214215, 2009). "SINV (TR339-eGFP) (+) strand RNA, infectious virus titers and infection rates transiently increased in mosquitoes following dsRNA injection to cognate Ago2, Dcr2, or TSN mRNAs." (PMID 18366655, 2008). "Enrichment analysis showed a significant enrichment of ribosomes and other processes in AGO2 immunoprecipitates in both infected and non-infected cells, although infection seems to decrease the significance of the association." (PMID 39899642, 2025). "However, upon infection with FgGMTV1, most of these mutants, with the exception of ago2, displayed elevated sensitivity to SDS compared to PH-1." (PMID 40518142, 2025). "Interestingly, 4 days post BinJV/BinJ-ZIKV infection and 1 day post ZIKV superinfection, Aag2 Ago2-deficient cells infected with either BinJV or BinJ-ZIKV started to show CPE." (PMID 39845567, 2025). "Indeed, the decline in IFNB production coincided with the translocation of AGO2 into the nucleus at 8 h post-infection, suggesting a potential contribution of nuclear AGO2 in the downregulation of antiviral IFN-I production." (PMID 40219968, 2025). "In contrast to Dcr2 deficient C6/36 cells, we were unsuccessful in generating persistently infected Ago2-deficient Aag2 cells, which might suggest differential roles for Dcr2 and Ago2 in cellular responses to infection." (PMID 39845567, 2025). "To probe to the underlying mechanism governing the infection-induced mortality in Ago2−/− mutants, we compared the whole transcriptomes of MAYV-infected Ago2−/− and WT females, as well as uninfected Ago2−/− and WT females." (PMID 37723154, 2023).
infection (continued). "Notably, ago2 was significantly (p = 0.019) although slightly (mean ± SD values of 0.759 ± 0.0523) downregulated on day 5 after infection." (PMID 37243270, 2023). "The siRNAi genes ago2 and dcr2 displayed a brief upregulation following infection." (PMID 37243270, 2023). "At the later stage of the infection, however, AGO2 expression declined." (PMID 37603044, 2023). "We performed independent natural infections of various Ago2 knockout mutant lines and the control (the parental Cas9 line) mosquitoes with different arboviruses, including two flaviviruses (DENV2 and ZIKV) and one alphavirus (MAYV) through blood meal." (PMID 37723154, 2023). "We also report that hyper-infection of Ago2 knockout mosquitoes stimulated a broad-spectrum antiviral immunity, including apoptosis, which may counteract infection." (PMID 37723154, 2023). "One explanation for why we did not observe differences between the siControl and siAGO2 group during vehicle treatment may be that while AGO2/RNAi is inhibited at the time of infection, its activity is restored by the time of sample collection." (PMID 35377915, 2022). "Continued knockdown of Ago2 protein was observed at 11 weeks post-infection with Ago2 Western blot." (PMID 35301367, 2022). "Similarly, silencing or knockout of Ago2 or Dcr2 induced an increase in infection by the tested arthropod-borne alphaviruses." (PMID 35171691, 2022). "In addition, this infection model has previously been successfully used to study the role of Ago2 and Dicer2 in antiviral immunity." (PMID 35891422, 2022). "To determine if Ago2 plays a direct role in Lp-sRNA-mediated gene silencing, we analyzed whether Lp-sRNAs and in particular RsmY directly interact with human Ago2 during infection." (PMID 35140216, 2022). "Similarly, the preferential accumulation of 21-nt 5′ uracil sRNAs in germinated spores and during early infection correlates with high-level expression of AGO2 and relatively low expression of AGO1." (PMID 34526021, 2021). "During infection, double-stranded RNAs that form during viral replication and infection are cleaved by the enzyme Dicer 2 (Dcr2) into virus-specific 21 nt vsiRNAs, which are subsequently loaded into Argonaute 2 (Ago2)." (PMID 34205194, 2021). "Interestingly, we did not observe changes in transcript expression levels for Dcr-2 and Ago-2 in any strain and for any virus and mode of infection." (PMID 32194567, 2020). "The conclusion was substantiated in another set of experiments where cells were transfected with siRNAs against PP2A, and an increase in Ago2 phosphorylation and decrease in Ago2‐bound miRNA content were noted in siPP2A‐treated cells compared to control siRNA‐treated cells upon Ld infection." (PMID 32031337, 2020). "These previous studies may help reveal the mechanism through which AGO2-knockdown alters the expression of endogenous genes and which host and viral genes involved in the development of necrotic symptoms during infection with PVX." (PMID 33032637, 2020). "Interestingly, a recent study in which D. melanogaster is used as a model to investigate Zika virus-insect interactions, showed an increased level of Dcr-2 and Ago-2 transcripts after infection." (PMID 32194567, 2020). "Do mammalian viruses encode VSRs that suppress AGO2, and what is the course of infection of virus mutants lacking this activity?" (PMID 31100912, 2019). "We speculate that reduced PRMT5 expression during infection may lead to reduced arginine methylation of AGO2, resulting in accumulation of both AGO2 and, via reduced interaction with TSNs, accumulation of AGO2-associated sRNAs, to promote plant immunity." (PMID 30783097, 2019).